BRD4 (bromodomain containing 4)
Diseases named in the same sentence as BRD4 in open-access papers (continued):
Sharing a sentence is not in itself a finding about the gene and the disease.
cancer (continued). "Besides providing novel insights into the molecular mechanisms of BRD4 inhibition in the regulation of PD-1 expression and PD-1-mediated inhibition of T-cell function, this study inspires thought on the dual effect of target inhibition BRD4 for cancer immunotherapy." (PMID 35918330, 2022). "Moreover, we speculate that cancer cells with high BRD4 expression may depend more on the regulatory mechanism described here." (PMID 35453346, 2022). "Importantly, as will be discussed in this review, (partial) inhibition of the various transcription-associated CDKs and BRD4 does not affect global transcription, but rather results into gene-specific effects that can be exploited for cancer therapy." (PMID 36139513, 2022). "The N-terminal bromodomain of BRD4 recognizes acetylated lysine on nucleosome histones, and BRD4 interacts with P-TEFb (positive transcription elongation Factor b) to facilitate the transcription of several oncogenes, such as c-myc, which contribute to the proliferation of cancer cells." (PMID 35135529, 2022). "Therefore, BRD4 inhibition sensitizes cancer cells to various replication stress-inducing agents." (PMID 34540900, 2021). "However, some studies found that BET inhibitors led to the accumulation of BRD4 protein in cancer cells, which, together with the reversible nature of inhibitor binding, could prevent efficient BRD4 inhibition." (PMID 33888130, 2021). "In addition, kinase (CK2) and phosphatase (PP2A) that phosphorylate and dephosphorylate BRD4, respectively, to modulate its function in chromatin localization, transcription factor recruitment, and cancer progression have been reported (ChiangPhospho-BRD4, 2016)." (PMID 34540900, 2021). "It is not completely clear how BRD4 coordinates telomere maintenance, but it is known that BRD4 selectively controls the expression of telomerase reverse transcriptase in the presence of cancer-related promoter mutations." (PMID 34540687, 2021). "Taken together, their findings and ours suggest that BRD4 plays an important general role in regulating replication stress responses, and that the effect of BRD4 inhibitors alone on inducing DNA damage in cancer cells may depend on the basal level of oncogene-induced replication stress." (PMID 32796829, 2020). "Therefore, the overall tumor-promoting activity of Brd4 in cancer cells might result from the Pin1-mediated conformational change of Brd4, leading to more stabilized Brd4 and conformational change-associated transcriptional potential increase." (PMID 32266261, 2020). "Furthermore, the BRD4 inhibitor (+)-JQ1 (JQ1) has been shown to suppress the proliferation of cancer cells, indicating that JQ1 may be a new therapeutic agent for cancer treatment." (PMID 30988278, 2019). "Therefore, upregulation of BRD4 expression in cancer may result from histone methylation or acetylation." (PMID 30988278, 2019). "Similarly, the expression of BRD4 was higher in a total analysis of pan-cancer patients." (PMID 30988278, 2019). "Furthermore, we found that BRD4 expression was negatively associated with both ATG5 and LAMP1 expression in pan-cancer patients, indicating that JQ1 increases the expression of ATG5 and LAMP1 via the suppression of BRD4 expression, subsequently inducing ferritinophagy." (PMID 30988278, 2019). "Interestingly, BET inhibitors have also been shown to have an anti-inflammatory effect in the treatment of various inflammatory diseases and cancer, suggesting that BRD4 may have an active role in supporting inflammation." (PMID 30029633, 2018). "Thus, BRD4 is thought to be a rational target for cancer therapy." (PMID 29540837, 2018). "Thus, studies with BRD4 inhibitors indicated that the inhibition of general transcriptional machinery could be a therapeutic option for cancer." (PMID 29724031, 2018).
cancer (continued). "Thus, how inhibition of a global chromatin regulator as BRD4 may results in a such cancer selective targeting, it remains at least in part unclear." (PMID 30466442, 2018). "Interestingly these compounds could induce potent and preferential removal of Brd4 over a suitable concentration window, leaving the homologous Brd2 and Brd3 relatively untouched and leading to more Brd4-specific response in cancer cells [49••]." (PMID 27423045, 2016). "Thus, BRD4 is a promising drug target for the treatment of various cancers." (PMID 26596901, 2015). "Besides the chromosomal rearrangement-induced NUT midline carcinomas, other studies have also indicated that Brd4 may contribute to cancer development through different mechanisms." (PMID 24592384, 2014). "BRD4 may have been only called into play late as these cancers evolve to become more aggressive." (PMID 23303309, 2013). "Genomic data from six cancer types reveals a strong positive ASXL1-BRD4 relationship, with BRD4 occupying the ASXL1 promoter and thus pointing to a possible feed-forward mechanism." (PMID 41702923, 2026). "Because BRDT has been presumed to function similarly to BRD4, we initially investigated a potential compensatory role for BRDT in cancer." (PMID 40085698, 2025). "The finding that NRF2-dependent cancer cells are refractory to CBP/p300 inhibition distinguishes NRF2 from other transcriptional oncogene addictions (i.e., AR, BRD4-NUT)." (PMID 40369363, 2025). "BRD4 is a positive regulator of the MYC oncogene, the expression of which is deregulated in many cancers, and accumulating evidence supports the involvement of BRD4 in the progression of many malignancies." (PMID 41311847, 2025). "A promising strategy is the synergistic inhibition of TOPO-I, BRD4, and ABCG2, which involves the targeting of three critical mechanisms in cancer progression." (PMID 40429764, 2025). "The BET family is composed by BRD2, BRD3, BRD4, and BRDT, and plays important roles in cancer by directly regulating the expression of cancer-related genes such as MYC, and the transcription factor NF-κB." (PMID 41551874, 2025). "Inhibiting BRD4 increased TXNIP levels and suppressed protein UFMylation, resulting in cancer cell cycle arrest and increased vulnerability to ferroptosis." (PMID 41249136, 2025). "In normal and cancer cells, the HAT enzyme p300 mediates hyperacetylation of enhancer and super-enhancer to which BRD4 is recruited." (PMID 40319015, 2025). "BRD4, a member of the Bromo and Extra-Terminal (BET) family, represents a promising target for cancer treatment." (PMID 41249136, 2025). "By interfering with BRD4, UNI66 presents a mechanism to modulate HR activity, potentially overcoming resistance mechanisms and sensitizing cancer cells to treatment." (PMID 40308947, 2025). "Although Brd4 inhibitors, such as JQ1 are primarily applied in cancer therapy, recent studies suggest their novel therapeutic potential in neurological disorders." (PMID 40428426, 2025). "To determine if BRD4 and IRS2 inhibitors can modulate the BMMCs immunosuppressive cancer microenvironment into an immunocompetent one, we measured the expression of several key tumor‐related immune molecules at the transcriptional and translational levels." (PMID 40285526, 2025). "These insights into the multifaceted roles of BRD4 and the therapeutic potential of BET inhibitors underscore the ongoing progress in developing targeted and effective strategies for cancer treatment." (PMID 40308947, 2025). "In RET-fusion-positive cancers, BET inhibitors (e.g., JQ1) disrupt BRD4-mediated transcriptional elongation of RET, potentiating the effects of RET TKIs." (PMID 40599544, 2025).
cancer (continued). "In this study, we examined SMYD5 across multiple cancers, with a focus on LIHC, and investigated its interaction with BRD4 in LIHC progression." (PMID 40872497, 2025). "Based on this study, future investigations should explore BRD4-distinct BRDT functions and BRDT misexpression driving cancer pathogenesis." (PMID 40085698, 2025). "Treatment with dBET1 leads to the significant destabilization of the BRD4 protein, down-regulation of MYC, and inhibition of proliferation in cancer cells within the tumor." (PMID 40083325, 2025). "BET proteins (BRD2, BRD3, BRD4 and BRDT) serve as the readers of DNA acetylation and regulate the expression of key genes in cancer." (PMID 38893083, 2024). "Our attempt to reverse EMP in MM ECs using JQ1 was also unsuccessful, despite JQ1 targeting BRD4, a known activator of EMP transcription factors in some cancers." (PMID 39596117, 2024). "HDAC3 regulates PD-L1 expression at the transcriptional level through various transcriptional factors, including STAT3, bromodomain containing 4 (BRD4), and p65, while further inhibiting the STAT3 cascade in cancer cells." (PMID 39690423, 2024). "We further revealed that inhibitors targeting the Src, Mcl‐1, STAT3, BRD4, p300, PLK1, or class I HDACs significantly enhanced CDK9i‐induced cell death in various KRAS‐mutant cancers." (PMID 39254172, 2024). "BRD4 and CDK9 have complementary and intimately connected roles in enhancing oncogenic gene expression programs in a variety of cancer types, especially in the context of MYC-driven tumors." (PMID 39117800, 2024). "Numerous small-molecule inhibitors targeting BRD4, such as BMS-986158, OTX-015, JQ1, and GSK-525762, have been synthesised and used for treating cancers in clinical settings." (PMID 38229152, 2024). "By inducing BRD4 degradation, the nano-PROTAC effectively triggers apoptosis in MV-4–11 cancer cells." (PMID 38773495, 2024). "The higher BRD4 degradation activity and cytotoxicity of NGP-39 towards cancer cells is mainly due to the higher endogenous concentration of H2O2 in these cells, as characterized by the H2O2-responsive fluorescence probe." (PMID 38773495, 2024). "BRD1, BRD2, BRD3, BRD4, and BRD7-9 were significantly upregulated in tumor samples expressing high levels of p16, a surrogate biomarker for HPV-positive cancers, and the presence of HPV DNA through in situ hybridization, compared to normal samples (p<0.05)." (PMID 39301555, 2024). "Bromodomain-containing protein 4 (BRD4), a member of bromodomain and extraterminal (BET) family, is an epigenetic regulator that plays an important role in embryogenesis and cancer development." (PMID 38191874, 2024). "In recent years, the development of allosteric inhibitors targeting BRD4, such as ZL0590 (also known as POJ), have proven to be interesting in new therapeutic approaches of cancers." (PMID 39124901, 2024). "Overall, the traditional small-molecule BRD4 inhibitor JQ1 and the newly developed BET inhibitors show promising results in various human cancers." (PMID 38225241, 2024). "BRD4, similar to other BET family members, contains two bromodomains that recognize acetylated lysine and is more often overexpressed in inflammation and cancer." (PMID 39337472, 2024). "BET inhibitors displace BRD4 from the regulatory region to inhibit gene expression, and the antitumor efficacy of BET family inhibitors is particularly promising for cancers with increased expression of oncogenic transcription factors, such as c-Myc." (PMID 38225241, 2024). "Currently, there are many commercially available small-molecule inhibitors targeting BRD4, such as BMS-986158, OTX-015, JQ1, and GSK-52576 to treat cancers in the clinic." (PMID 38229152, 2024).
cancer (continued). "Only when both NQO1 and β-Lapachone are overexpressed simultaneously in cancer cells, the NGP-27 becomes activated and effectively degrades BRD4." (PMID 38773495, 2024). "BRD4 is a member of the BET family and plays a key role in regulating cell growth and cancer development by binding to acetylated lysine residues of histones and other proteins." (PMID 38565708, 2024). "ARGLU1 influences adenovirus replication and cancer cell chemoresistance by modulating promoter-proximal RNA polymerase II pausing and interacting with key proteins like JMJD6 and BRD4." (PMID 39066258, 2024). "Over the past several years, NSD3S has been established as an adaptor protein for important drivers of cancer, such as MYC, BRD4, and CHD8." (PMID 38256018, 2024). "A diverse array of preclinical studies indicates that SE inhibitors, such as the BRD4 inhibitor JQ1, exhibit significant potential in repressing seRNA transcription and impeding cancer proliferation." (PMID 39690143, 2024). "Next, we performed BRD4 ChIP-seq in the cancer cells and found that more than 50% of REV-ERBα ChIP-seq peaks overlapped with those of BRD4." (PMID 39383000, 2024). "Lastly, we observed that the radioresistance of cancer cells was significantly reduced when irradiation was combined with ARV-771, a BRD4 de-stabilizer." (PMID 38874522, 2024). "BRD4 is known to activate the transcription of MYC oncogene and various receptor tyrosine kinases (RTK), contributing to cancer cell proliferation and survival signaling." (PMID 38617536, 2024). "This targeted release facilitates tumor-specific BRD4 degradation, offering a highly selective and efficient approach to PROTAC-based cancer therapy." (PMID 39649701, 2024). "M6A‐related genes such as BRD4, MYC, SOCS2, and EGFR are frequently involved in the progression of cancers including LUAD." (PMID 39323079, 2024). "BRD4, a bromodomain and extraterminal (BET) protein, is deregulated in multiple cancers and has emerged as a promising drug target." (PMID 38191874, 2024). "Treatments, especially for NUT carcinoma, have been undergoing development during the last decades; however, these drugs mostly target genes fused to NUTM1 in cancer; for example, BET inhibitors target BRD4 in the BRD4-NUTM1 fusion protein." (PMID 39013578, 2024). "Next to several well-known cancer stemness facilitators, including TRIM28 or BRD4, various other BrD proteins were recently proven to sustain stem cell-like phenotype via the utilization of distinct mechanisms." (PMID 36674511, 2023). "Taken together, these results showed that the Nano‐PROTACs strategy enhances the efficiency of BRD4 degradation by improving the permeability and accumulation of ARV‐771 PROTACs in cancer cells." (PMID 37066758, 2023). "In recent years, BRD4 has been identified as the major BRD involved in oncogenesis and consequently has been the focus of several anti-cancer drug discovery efforts." (PMID 36768967, 2023). "Preclinical studies have shown promising results for dual BRD4 and PLK1 inhibitors in treating a variety of cancer types." (PMID 37765111, 2023). "As bromodomain containing 4 (BRD4) is a well-known and effective BET protein and is well acknowledged in cancers for its oncogenic roles, we tested the relationship of NPM1 and BRD4." (PMID 37875480, 2023). "The transcriptional levels of BET (BRD1,BRD2,BRD3, BRD4 and BRDT) were compared between cancer and normal samples in GEPIA database." (PMID 36711038, 2023). "The simultaneous inhibition of BRD4 and PLK1 enzymes by a single small molecule has shown a synergistic effect in the treatment of several types of cancers by increasing apoptosis and decreasing cancer cell proliferation with reduced toxicity." (PMID 37765111, 2023). "BRD4 is the most extensively studied member of the BET family, and has emerged as an attractive therapeutic target for cancer therapy." (PMID 36733715, 2023).
cancer (continued). "This analysis focused on the functionally significant components of the multimeric RNAPII complex, including BRD4, HEXIM1, Spt5, NELF-A, Cyclin T, CDK9, LARP-7, and Caspase-8, which collectively serve as a regulatory hub in gene expression in cancer cells." (PMID 38201534, 2023). "In a variety of types of malignant tumors, there is a consistent over-expression of multiple BCPs genes on which tumors depend, including BRD2, BRD4, ATAD2, KAT2A, etc.." (PMID 37142850, 2023). "Cancer cells were treated with Tz-thalidomide (10 μM) for 18 h followed by (+)-JQ1-TCO (3 μM) for another 18 h, or vice versa, to give rise to complete Brd4 degradation." (PMID 37049806, 2023). "Several BRD4 inhibitors, known as Bromo‐ and Extra‐Terminal domain (BET) inhibitors (BETi), have been tested in multiple cancer models, and 30 clinical trials are currently ongoing to evaluate their anticancer efficacy." (PMID 37937685, 2023). "The BRD4 inhibitor (JQ1) competes with BRD4 for binding to acetylated lysines, displacing BRD4 from super-enhancers within the MYC oncogene and reducing MYC expression, resulting in anti-cancer effects in hematopoietic cancers, PDAC and MYCN-driven cancers." (PMID 37755397, 2023). "Here, we show that LOXL2 expression can predict the outcome of BETi treatment in cancer cells, suggesting a functional interaction between LOXL2 and BRD4." (PMID 37937685, 2023). "Multiple BRD4 protein small-molecule inhibitors, such as JQ1, have been developed and have shown promising anticancer results in experimental and clinical cancer studies." (PMID 36733715, 2023). "Although TGF-β signaling plays a vital role in the progression of tumorigenesis, the link between BRD4 and TGF-β in cancer remains mysterious." (PMID 37737256, 2023). "In the context of cancer, the dysregulation of transcriptional elongation holds profound implications, with BRD4 (Bromodomain-containing protein 4) emerging as a pivotal contributor in this context." (PMID 38201534, 2023). "We first compared the expression levels of BRD2, BRD3, and BRD4 in ACC patients with different cancer stages and found that BRD3 and BRD4 transcript levels were significantly upregulated in patients with ACC." (PMID 36793283, 2023). "Mechanistically, while BRD4 inhibitors up-regulate RSK3 to activate the mTOR pathway, mTOR inhibitors block this cell survival signaling and enhance BRD4 inhibitor-mediated cancer cell apoptosis." (PMID 38135679, 2023). "Considering this, we propose that SSO‐QPOP can guide the co‐development of effective cancer therapeutics, such as CHK1 and BRD4 inhibitors against MYC‐driven HCC." (PMID 36684069, 2023). "The simultaneous targeting of BRD4 and TOP1 with a panel of BET inhibitors and TOP1 poisons, respectively, synergistically inhibited cancer cell growth in vitro." (PMID 37831776, 2023). "It is noteworthy that both BRD4 and PLK1 play important roles in mitosis, as well as the finding that inhibition of BRD4 and PLK1 can sensitize cancer cells to DNA-damaging agents such as radiation and chemotherapy drugs." (PMID 37765111, 2023). "Subsequently, pre-mACSL3 splicing mediated by BRD4 and SRPK2 ensures the expression abundance of ACSL3 in cancer cells." (PMID 37993451, 2023). "SHK suppresses NF-κB-regulated gene products and pyruvate kinase-M2 (PKM2), induces immunogenic cell death, and inhibits cancer glucose metabolism, while JQ1 selectively inhibits the Bromodomain-containing protein 4 (BRD4) signaling pathway." (PMID 37242604, 2023). "We first compared the expression levels of BRD2, BRD3, and BRD4 in ACC patients with different cancer stages and found that the BRD3 (stage 4) and BRD4 transcript levels were significantly upregulated in patients with ACC (P < 0.05)." (PMID 36793283, 2023). "Dual inhibition of BRD4 and PI3K repressed IL-4-driven macrophages and their immunosuppression effect in syngeneic and spontaneous murine cancer models." (PMID 36627707, 2023).